CEP290 (centrosomal protein 290)
Description:
Involved in early and late steps in cilia formation. Its association with CCP110 is required for inhibition of primary cilia formation by CCP110. May play a role in early ciliogenesis in the disappearance of centriolar satellites and in the transition of primary ciliar vesicles (PCVs) to capped ciliary vesicles (CCVs). Required for the centrosomal recruitment of RAB8A and for the targeting of centriole satellite proteins to centrosomes such as of PCM1. Required for the correct localization of ciliary and phototransduction proteins in retinal photoreceptor cells; may play a role in ciliary transport processes (By similarity). Required for efficient recruitment of RAB8A to primary cilium. In the ciliary transition zone is part of the tectonic-like complex which is required for tissue-specific ciliogenesis and may regulate ciliary membrane composition (By similarity). Involved in regulation of the BBSome complex integrity, specifically for presence of BBS2, BBS5 and BBS8/TTC8 in the complex, and in ciliary targeting of selected BBSome cargos. May play a role in controlling entry of the BBSome complex to cilia possibly implicating IQCB1/NPHP5. Activates ATF4-mediated transcription.
Synonyms: CT87; BBS14; KIAA0373; NPHP6; FLJ13615; 3H11Ag; rd16; JBTS5; SLSN6; LCA10; MKS4; POC3
Tractability: Antibody: its Gene Ontology location is reachable by antibodies, with high confidence. PROTAC: UniProt records ubiquitination sites on it; ubiquitination databases record sites on it; its protein half-life has been measured.
Gene: Protein-coding gene on chromosome 12 (88,049,016 to 88,142,099, reverse strand). Ensembl gene ENSG00000198707.
Subcellular location: Cytoplasm, cytoskeleton, microtubule organizing center, centrosome; Cytoplasm, cytoskeleton, microtubule organizing center, centrosome, centriolar satellite; Nucleus; Cell projection, cilium; Cytoplasm, cytoskeleton, cilium basal body; Cytoplasm, cytoskeleton, microtubule organizing center, centrosome, centriole; Cytoplasmic vesicle
Subcellular location (Human Protein Atlas): Basal body; Centrosome; Mid piece; Primary cilium; Principal piece
Pathways (Reactome):
Cell Cycle: AURKA Activation by TPX2; Loss of Nlp from mitotic centrosomes; Loss of proteins required for interphase microtubule organization from the centrosome; Recruitment of NuMA to mitotic centrosomes; Recruitment of mitotic centrosome proteins and complexes; Regulation of PLK1 Activity at G2/M Transition
Immune System: Neutrophil degranulation
Organelle biogenesis and maintenance: Anchoring of the basal body to the plasma membrane
Gene Ontology:
Molecular function: identical protein binding; microtubule minus-end binding; protein binding
Biological process: cilium assembly; positive regulation of DNA-templated transcription; positive regulation of intracellular protein transport; regulation of establishment of protein localization; camera-type eye development; ciliary transition zone assembly; eye photoreceptor cell development; hindbrain development; kidney development; non-motile cilium assembly; otic vesicle formation; pronephros development; protein localization to ciliary transition zone; protein transport
Cellular component: centriolar satellite; centriole; centrosome; ciliary transition zone; cytoplasm; cytosol; membrane; nucleus; protein-containing complex; cytoplasmic vesicle; extracellular region; MKS complex; photoreceptor connecting cilium; specific granule lumen; cilium
Genetic constraint (gnomAD): Loss-of-function variants: 149 observed, 156.05 expected, observed/expected ratio (o/e) 0.95, 90% interval 0.83 to 1.09. The upper end of that interval is the gene's LOEUF score, 1.09, which puts it in group 4 of 6, group 1 being the genes least tolerant of losing a copy. Missense variants: 1,462 observed, 1,480.9 expected, observed/expected ratio (o/e) 0.99, 90% interval 0.94 to 1.03. Synonymous variants: 520 observed, 487.23 expected, observed/expected ratio (o/e) 1.07, 90% interval 0.99 to 1.15.
Gene-disease validity (ClinGen):
ClinGen rates the evidence that CEP290 causes each of these diseases.
CEP290-related ciliopathy (autosomal recessive): Definitive. A ciliopathy caused by biallelic variants in the CEP290 gene.
Homologues: Orthologues: chimpanzee CEP290 (98% identical), macaque CEP290 (98% identical), dog CEP290 (92% identical), rabbit CEP290 (90% identical), pig CEP290 (89% identical), mouse Cep290 (87% identical), guinea pig CEP290 (87% identical), rat Cep290 (87% identical), tropical clawed frog cep290 (63% identical), zebrafish cep290 (57% identical).
Diseases named in the same sentence as CEP290 in open-access papers:
CEP290 is named in the same sentence as 115 diseases in open-access papers, as found by Europe PMC text mining. Sharing a sentence is not in itself a finding about the gene and the disease. The quoted sentences say what the papers report.
Leber congenital amaurosis (89 papers, 2009 to 2026). Leber congenital amaurosis (LCA) is a retinal dystrophy defined by blindness and responses to electrophysiological stimulation (Ganzfeld electroretinogram (ERG)) below threshold, associated with severe visual impairment within the first year of life. "Recently, we identified reserpine as a lead molecule for maintaining rod survival in mouse and human retinal organoids as well as in the rd16 mouse, which phenocopy Leber congenital amaurosis caused by mutations in the cilia-centrosomal gene CEP290." (PMID 40231721, 2025). "The milestone BRILLIANCE trial tested the efficacy and safety of EDIT-101, which is a CRISPR-targeted therapy for the CEP290 gene mutation for Leber Congenital Amaurosis 10 (LCA10)." (PMID 40362317, 2025). "One such therapy, EDIT-101, is designed to correct mutations in the CEP290 gene responsible for Leber congenital amaurosis 10 (LCA10), a severe retinal dystrophy." (PMID 40110250, 2025). "CRISPR/Cas9 was applied to correct mutations in RPGR and CEP290 associated with Retinitis Pigmentosa and Leber congenital amaurosis." (PMID 39439625, 2024). "In our cohort, we identified one JS patient affected by retinal dystrophy, while another JS patient presented with Leber congenital amaurosis, a condition attributed to CEP290 gene mutations in approximately 30% of cases." (PMID 38671609, 2024). "Genetic variants of CEP290 are associated with Leber's congenital amaurosis in humans and photoreceptor degeneration in zebrafish." (PMID 38813692, 2024). "Biallelic pathogenic variants in the cilia-associated gene CEP290 cause non-syndromic Leber congenital amaurosis 10 (LCA10) and syndromic diseases, where the retina is also affected." (PMID 37371046, 2023). "Mutations in CEP290 are associated with various diseases, such as the devastating blinding disease Leber’s congenital amaurosis, nephronophthisis, Senior Lǿken syndrome, Joubert syndrome, Bardet–Biedl syndrome, and lethal Meckel–Gruber syndrome." (PMID 37737843, 2023). "For example CEP290 pathogenic variants can be responsible of multiple phenotypes attributed to cilia dysfunction including Joubert syndrome, Leber congenital amaurosis, Meckel syndrome, and Senior‐Loken syndrome." (PMID 35488810, 2022). "The clinical test has assessed the subretinal AAV-facilitated transport of SaCas9 combined with a couple of gRNAs to mark a profound intronic mutation in the CEP290 gene in order to treat type 10 Leber congenital amaurosis (NCT03872479)." (PMID 36232782, 2022). "For example, CEP290 mutations can cause a spectrumof phenotypes that range from retinal degeneration (Leber congenital amaurosis) to embryoniclethality (Meckel–Gruber syndrome), and there are often noclear correlations between patient genotype and phenotype." (PMID 34169321, 2021). "CEP290 deficiency in humans can be as mild as isolated blindness (Leber's congenital amaurosis) or as severe as perinatal lethality (Meckel–Gruber syndrome)." (PMID 34155518, 2021). "Defects in the gene encoding centrosomal protein of 290 kDa (CEP290) are the leading genetic cause of the severe blinding condition known as Leber congenital amaurosis (LCA)." (PMID 34520396, 2021). "Another highly pertinent target is the recurrent c.2991+1655A>G variant in intron 26 of the gene CEP290, which was associated with autosomal recessive Leber congenital amaurosis." (PMID 33807610, 2021). "Mutations in human CEP290 are commonly associated with Leber's congenital amaurosis, an isolated degenerative blindness, but can also lead to outcomes as severe as Meckel–Grüber syndrome (failed neural tube closure, encephalocele and perinatal lethality)." (PMID 34155518, 2021). "Allergan and Editas Medicine have recently launched the Brilliance clinical trial (NCT03872479) for Leber congenital amaurosis (LCA) 10 patients with an intronic mutation in CEP290 gene." (PMID 33193648, 2020).
Leber congenital amaurosis (continued). "rd16 is a mouse model with a rapidly degenerating retina due a spontaneous deletion in the Cep290 gene, the most frequently mutated gene in Leber congenital amaurosis." (PMID 31138784, 2019). "The first splicing modulation strategy described for a retinal disease was targeting a recurring deep-intronic variant (c.2991+1655A>G) in the CEP290 gene, underlying recessive Leber congenital amaurosis (LCA; MIM:611755)." (PMID 31197102, 2019). "To test this we targeted cleavage to the site of a point mutation in an intron of the CEP290 gene that causes a type of Leber congenital amaurosis, LCA10." (PMID 30850604, 2019). "Leber congenital amaurosis as caused by mutations in centrosomal protein 290 kDa (CEP290) has been shown to cause a ciliopathy defect in both RPE cells and photoreceptors." (PMID 30572641, 2018). "Mutations in the CEP290 gene is one of the most common causes of Leber congenital amaurosis (LCA), a severe retinal degenerative disease with early onset and rapid progression." (PMID 29868583, 2018). "Genetic deficiency in CEP290 is responsible for 15% of Leber congenital amaurosis (LCA) cases and has been implicated in other ciliopathies including SLS, nephronophthisis, Joubert syndrome, Bardet-Biedl syndrome (BBS), and Meckel syndrome (MKSS)." (PMID 26124960, 2015). "This study investigated the centrosomal protein, 290-KD (CEP290) associated genotype and ocular and extra-ocular phenotype in 18 patients with Leber congenital amaurosis (LCA)." (PMID 22355252, 2012). "CEP290 mutations are a common cause of isolated Leber's congenital amaurosis, accounting for ∼20% of patients." (PMID 23028714, 2012). "While Luxturna has paved the way for gene therapy in retinal diseases, it is important to highlight other promising therapies in clinical trials, such as those targeting X-linked retinitis pigmentosa (RPGR) and Leber congenital amaurosis (CEP290), to provide a broader view of future treatments." (PMID 39439625, 2024). "Splice-switching AONs have already made a mark in the field of therapies for IRD with ongoing clinical trials for Leber congenital amaurosis due to a deep-intronic mutation in CEP290 c.2991+1655A>G and retinitis pigmentosa caused by coding variants in exon 13 of USH2A." (PMID 36552712, 2022). "Gene editing approaches hold promise to treat and cure congenital blindness; an ongoing clinical trial (NCT03872479) uses AAV-delivered Cas9 nucleases to disrupt an aberrant splice site in CEP290 that is associated with rare Leber congenital amaurosis 10 (LCA10)." (PMID 35021064, 2022). "Notably, inactivating mutations in CEP290 cause Leber congenital amaurosis (LCA), an early-onset severe retinal degeneration, in humans." (PMID 33961633, 2021). "CEP290 mutations are the commonest monogenic form of Leber's congenital amaurosis (LCA)." (PMID 23028714, 2012). "Mutations in CEP290 may cause a wide spectrum of human disease ranging from isolated Leber's congenital amaurosis to JSRD, Meckel syndrome (MKS) and Bardet-Biedl syndrome (BBS)." (PMID 23028714, 2012). "For example, RPGR exists in complex with NPHP5 (or IQ domain containing calmodulin binding protein [IQCB1]; SLSN), centrosomal protein of 290 kDa (CEP290)/NPHP6 (Leber congenital amaurosis, SLSN, JBTS), and NPHP8/RPGRIP1-like (RPGRIP1L; mutated in JBTS and Meckel-Gruber syndrome) in the retina." (PMID 20664800, 2010). "For example, mutations in the CEP290 gene account for 15–20% of Leber congenital amaurosis (LCA) cases." (PMID 40362317, 2025). "One such retinal disorder is Leber congenital amaurosis (LCA), a monogenic disorder that leads to childhood blindness due to a bi-allelic loss-of-function mutation in the CEP290 gene." (PMID 38362491, 2024). "Cep290 is an intriguing cilia gene associated with several ciliopathies, including Leber congenital amaurosis (LCA), Senior–Loken syndrome (SLS), Joubert syndrome (JBTS), MKS, and Bardet–Biedl syndrome (BBS)." (PMID 38442096, 2024).
Leber congenital amaurosis (continued). "A deep intronic CEP290 variant (c.2991 + 1655A > G) resulting in aberrant splicing was identified in 16 (21%) of 76 unrelated patients with Leber congenital amaurosis (LCA)." (PMID 37628633, 2023). "For example, leber congenital amaurosis (LCA) is an inherited retinal degenerative disease caused by mutations in different genes, including CEP290, GUCY2D, CRB1, and RPE65." (PMID 36556333, 2022). "Leber congenital amaurosis type 10 (LCA10), the most common type of LCA, is an autosomal recessive disorder caused by a mutation in the biallelic gene CEP290." (PMID 36483767, 2022). "Leber congenital amaurosis (LCA) retinal dystrophy is linked with juvenile blindness or severe visual impairment due to intronic mutation in various genes including centrosomal protein 290 (CEP290)." (PMID 34631795, 2021). "Mutations in CEP290 cause several ciliopathies ranging from nonsyndromic retinal degeneration, i.e., Leber Congenital Amaurosis (LCA), to syndromic disorders including, Senior–Loken syndrome (SLS), Joubert syndrome (JBTS), MKS, and Bardet–Biedl syndrome (BBS)." (PMID 33370260, 2020). "Mutations in the CEP290 gene are reported as the most common (20%) cause of Leber congenital amaurosis (LCA) and they are more frequently associated with severe forms of retinopathies." (PMID 31877679, 2019). "Nevertheless, patients with KIAA0586-related JBTS should be investigated for signs of retinal degeneration, and given that mutations in the JBTS gene CEP290 may cause non-syndromic Leber congenital amaurosis, KIAA0586 represents a candidate gene for isolated retinopathies." (PMID 26386247, 2015). "Mutations in the CEP290 (cilia-centrosomal protein 290 kDa) gene in Leber congenital amaurosis (LCA) cause early onset visual loss but retained cone photoreceptors in the fovea, which is the potential therapeutic target." (PMID 24671090, 2014). "A type of Leber congenital amaurosis 10 (LCA10), a rare inherited retinal dystrophy, is also caused by mis-spliced exon, which is stemmed from CEP290 IVS26 mutation." (PMID 37027099, 2023). "Mutations in CEP290 cause a variety of ciliopathies, including ‘Joubert syndrome’ (JBTS), ‘Leber congenital amaurosis’ (LCA) and ‘Meckel syndrome’ (MKS)." (PMID 33860332, 2021). "Leber congenital amaurosis (LCA) is a rare childhood inherited retinal disease, with its more severe form caused by an intronic splice mutation in CEP290." (PMID 34948465, 2021). "Centrosomal protein 290 (CEP290) is essential for the assembly of ciliary transition zone, and its mutations are frequently found in Leber congenital amaurosis (LCA), an autosomal recessive childhood blindness disorder." (PMID 34448530, 2021). "As observed previously in nasal cilia of some nonsyndromic Leber congenital amaurosis patients, CEP290-depleted cells display some enlarged cilia, consistent with aberrant gating at the TZ." (PMID 32163404, 2020). "Most notably, mutations in CEP290 (MKS4) can also occur in patients with NPHP, Senior-Løken syndrome (SLSN), JBTS, BBS, COACH syndrome, and Leber congenital amaurosis." (PMID 29209597, 2017). "Among those genes, CEP290 accounted for the highest proportion of pathogenic alleles in cases (AC = 12), which was reported to cause Bardet–Biedl syndrome [MIM: 615991] and Leber congenital amaurosis [MIM: 611755] with early-onset retinal degeneration." (PMID 39112444, 2024). "Mutations in CEP290 gene have been associated with a wide range of ciliopathies, ranging from lethal syndromes (Meckel-Grüber syndrome MIM#611134) to non-syndromic retinal degeneration (Leber congenital amaurosis MIM#611755)." (PMID 25761237, 2015). "CEP290 encodes for a centrosomal protein, mutations of which have been linked to several ciliopathies, including BBS, Joubert syndrome, nephronophthisis, and Leber Congenital Amaurosis." (PMID 23351793, 2012).
Leber congenital amaurosis (continued). "Two clinical disorders associated with CEP290 gene mutations include syndromic retinopathy (Joubert Syndrome and Related Disorders, JSRD) and non-syndromic Leber congenital amaurosis (LCA)." (PMID 38927641, 2024). "Machine learning techniques have recently been used to predict treatment potential in two forms of Leber congenital amaurosis (LCA) caused by mutations in CEP290 or IQCB1 (NPHP5), that had little or no measurable vision but some measurable central retinal structure." (PMID 32848570, 2020). "Mutations in these ciliary genes are implicated in photoreceptor degeneration related ciliopathies, such as RPGRIP1 in cone dystrophy (CD)/cone-rod dystrophy (CRD), LCA5 and CEP290 in Leber congenital amaurosis (LCA), Fam161A and OFD1 in RP." (PMID 27196396, 2016). "This study only included patients with rod-cone dystrophies or Leber congenital amaurosis (LCA) harboring specific culprit genes (DHDDS, CRB1, and CEP290) and at least 8 eyes that with BCVA measuring better or equivalent to 6/38." (PMID 40455038, 2025). "This could result in structural defects that are particularly detrimental to the outer segment, impairing photoreceptor maintenance rather than formation, and clinically manifesting as late-onset RP and not as congenital retinal disease, as in CEP290-associated Leber congenital amaurosis." (PMID 36862503, 2023). "Complete loss of function of both CEP290 alleles typically leads to Joubert syndrome, whereas patients with Leber congenital amaurosis and early onset IRD are expected to have a small amount of residual CEP290 activity." (PMID 37642804, 2023). "The most common form of LCA, Leber congenital amaurosis type 10 (LCA10), is caused by loss-of-function mutations in the centrosomal protein 290 kDa (CEP290) gene, which encodes the protein necessary for the assembly of the connecting cilium of photoreceptors and phototransduction." (PMID 36556333, 2022). "CRISPR-Cas9 gene-editing technology is being tested in clinical trials in vitro for Leber’s congenital amaurosis 10 (LCA10), which results in blindness, to correct the CEP290 gene, which is responsible for the disease." (PMID 33916893, 2021). "ROs have also been used to identify the disease mechanisms of Leber’s congenital amaurosis (LCA)-related RPE65, CEP290, AIPL1 and CRX." (PMID 34719743, 2021). "Moreover, another large gene, CEP290, can be rescued on the mRNA level by antisense oligonucleotides (AONs; QR-110 for Leber congenital amaurosis (LCA), with CEP290; QR-421a for LCA with USH2A)." (PMID 32545533, 2020). "To date, variants of CEP290 have been demonstrated with several genetic disorders more than JBST5, such as Leber congenital amaurosis (LCA10, OMIM#611755), Meckel syndrome type 4 (MKS4, OMIM#611134), and Bardet-Biedl syndrome 14 (BBS14, OMIM#615991)." (PMID 32600475, 2020). "Interestingly, certain genes commonly associated with Leber congenital amaurosis/early-onset severe retinal dystrophy (LCA/EOSRD) in Western Europe, such as CEP290 and RPE65, were only minimally (CEP290) or not at all (RPE65) involved in the Chilean cohort." (PMID 38892339, 2024). "On the other hand, URECs and fibroblasts derived from patients with Leber congenital amaurosis (LCA), a severe form of retinal degeneration with no renal or cerebellar manifestations, displayed detectable levels of full-length CEP290, normal ciliogenesis and cilia morphology." (PMID 31346239, 2019).